EGFR (epidermal growth factor receptor)
Diseases named in the same sentence as EGFR in open-access papers (continued):
Sharing a sentence is not in itself a finding about the gene and the disease.
tumor (continued). "Surprisingly, compound 9c heightened the activation of ERK, probably due to the activation of alternative pathways in tumor cells resulting from the potent inhibition of EGFRs, as it has reported that the EGFR inhibitor causes the activation of ERK signaling mediated by SRC bypass." (PMID 40076615, 2025). "These interactions are associated with enhanced adhesion, migration, and invasive potential of tumor cells, suggesting that EGFR mutation may promote tumor progression and immune evasion by modulating specific adhesion-related communication axes." (PMID 41164195, 2025). "EGFR, a member of the receptor tyrosine kinase family, is mutated in various cancers, and the abnormal activation of its downstream signaling pathway plays an important role in tumor cell proliferation, survival, migration, and angiogenesis." (PMID 41472727, 2025). "Additionally, the organoid model effectively characterized the resistance mechanisms of tumor cells to chemotherapeutic agents, particularly the emergence of target mutations such as EGFR and HER2." (PMID 41113459, 2025). "Tumor cells with PIK3CA mutations are resistant to drugs targeting epidermal growth factor receptor (EGFR) or erythroblastic leukemia viral oncogene homolog 2 (ERBB2), but may be more sensitive to mTOR and PI3K inhibitors." (PMID 41040523, 2025). "Targeted therapies might also enhance the presentation of tumor antigens to immune cells, improving the priming of tumor-specific T cells as well as targeting EGFR, VEGFR, or BRAF, which are frequently mutated or dysregulated in GI cancers." (PMID 40943055, 2025). "Overall, these findings suggest that MGMT methylation is associated with improved survival but an increased risk of out-field recurrence, while EGFR amplification is linked to higher rates of marginal recurrence, potentially reflecting a more invasive tumor phenotype." (PMID 40722305, 2025). "For instance, one study reported that the prevalence of dual mutations rose to 3.49% after TKI treatment, supporting the hypothesis that dormant tumor cells harboring both mutations may proliferate after EGFR inhibition." (PMID 39852181, 2025). "Acquired resistance typically arises through a variety of mechanisms, including secondary mutations and persistent EGFR activation, alterations in downstream signaling pathways, phenotypic transformations, modifications in the tumor microenvironment, and immune dysregulation." (PMID 40003951, 2025). "The results showed that patients with a high proportion of HIP1R+, CDKN2A+, and IDHR132H+ tumor cells had a significantly better prognosis than those with a low proportion of positive tumor cells, while a high proportion of EGFR+ tumor cells was associated with a poor prognosis." (PMID 40264576, 2025). "attributed this observation to the higher prevalence of EGFR mutations among Asians compared to Caucasians, suggesting that ethnicity‐related differences in tumor biology and serum marker expression may underlie this phenomenon." (PMID 40856433, 2025). "Additionally, CT imaging features including tumor maximal diameter, location, density, ground-glass opacity, pleural retraction, and air bronchogram have been validated as predictive biomarkers for EGFR mutations." (PMID 40708937, 2025). "Activating mutations in EGFR, typically characterized as late events, might lead to a tumor that is more associated with the AC-like state leading to redundancy in high CDK4 expression levels." (PMID 39959305, 2025).
tumor (continued). "However, EGFR mutation determination still primarily relies on tissue-based testing, which is invasive, costly, and often limited by sampling insufficiency or tumor heterogeneity." (PMID 41417019, 2025). "Therefore, combining EGFR-TKIs with ICIs can enhance the response of a subpopulation of NSCLC patients with EGFRm tumours resistant to first-line TKIs despite the risk of additional adverse effects." (PMID 40149368, 2025). "Likewise, osimertinib, with significant efficacy in treating NSCLC with the EGFR T790M mutation, shows less consistent outcomes in other tumor contexts, underscoring the need to address co-occurring alterations and heterogeneous tumor ecosystems." (PMID 40075649, 2025). "Tumor-associated macrophages (TAMs) play a pivotal role in the development of EGFR-TKI resistance." (PMID 40003951, 2025). "First, environmental pressures within the tumor microenvironment may be regional, leading to the focal emergence of EGFRvIII and other EGFR mutations promoting angiogenesis through oncogenic signaling." (PMID 40197845, 2025). "Given that the EGFR signaling pathway played a key role in promoting cell cycle progression and DNA repair 34, the regulatory associations of these genes might affect tumor cell sensitivity to EGFR blockade, potentially impacting cetuximab efficacy." (PMID 40959565, 2025). "Mutation of a single amino acid in the epidermal growth factor receptor can determine whether tumor cells are sensitive or refractory to an anti-cancer drug." (PMID 39688410, 2025). "Activation of EGFR by phosphorylation is associated with tumor cell proliferation and invasion." (PMID 41346909, 2025). "Besides, the EGFR signaling pathway is a highly classical pathway in tumor immunity, closely associated with various forms of immune dysregulation in multiple types of cancer." (PMID 40463392, 2025). "Notably, CAV-1 modulates signal transduction of multiple tumor-associated pathways, including those mediated by Src family tyrosine kinases and epidermal growth factor receptor (EGFR), which are closely linked to cancer cell proliferation and migration." (PMID 41463331, 2025). "Dual-energy CT provides comprehensive tissue composition information, with its quantitative parameters reflecting tumor microstructural characteristics including vascularization, cellular density, and histopathological components - features potentially associated with EGFR mutation status." (PMID 41244899, 2025). "A statistically significant association was observed between the EGFR index and tumor response." (PMID 41676833, 2025). "Furthermore, phages can be genetically engineered to express peptides or antibodies that specifically target tumor-associated antigens, such as EGFR or GRP78, which are often overexpressed in various types of cancer." (PMID 40427029, 2025). "Therefore, for individualized treatment, it is essential to find EGFR mutations in patient tumor samples." (PMID 40332084, 2025). "As an example, a patient’s tumor may have developed heterogenous resistance to osimertinib, with some cells acquiring an EGFR C797S mutation that prevents osimertinib binding, and some cells entering a more quiescent, or drug-tolerant persister state." (PMID 41175446, 2025). "EGFR overexpression is closely linked to tumor angiogenesis and local metastasis." (PMID 40135231, 2025).
tumor (continued). "These selective pressures may favor specific EGFR mutations, such as EGFRvIII, in EGFR‐amplified tumor cells at later stages of tumor development." (PMID 40197845, 2025). "Fourth, other important prognostic and biological factors—such as molecular tumor profiles (EGFR, KRAS, ALK mutations), PD-L1 expression, or systemic inflammatory indices beyond NLR/PLR/LMR—were not incorporated into the analysis, potentially limiting mechanistic interpretation." (PMID 41010912, 2025). "EGFR amplification has been implicated in resistance to anti-EGFR therapies and may contribute to tumor proliferation, angiogenesis, and organotropism, potentially facilitating ocular dissemination via choroidal vasculature." (PMID 40842629, 2025). "Our patient’s tumor also harbored EGFR p.G598V and p.T363I pathologic variants." (PMID 40724977, 2025). "In human high-grade serous ovarian cancer, elevated expression of the sialidase NEU4 is associated with tumor metastasis and poor survival, which in this tumor type might be linked to specific desialylation of N196 in EGFR." (PMID 40885395, 2025). "The increase in EGFR expression caused by HIF1a expression, associated with targeted drug delivery to the tumor, may justify the sensitization to cetuximab." (PMID 40149887, 2025). "From a tumor biology perspective, these characteristics may stem from the ability of EGFR mutations to amplify downstream signaling cascades, particularly MEK/ERK and PI3K/AKT/mTOR pathways." (PMID 41415549, 2025). "To address these limitations, we propose a novel strategy for profiling EGFR mutations at the protein level by directly detecting mutant EGFR protein on CTCs, which may effectively overcome the challenges posed by tumor heterogeneity." (PMID 41439947, 2025). "BRAF mutations not only significantly influence the effects of anti–epidermal growth factor receptor monoclonal antibody treatment but are also closely associated with tumor invasiveness and metastasis, making them crucial indicators for evaluating disease progression and treatment prognosis." (PMID 40680189, 2025). "Regarding tumor differentiation, this study found that EGFR mutations were more common in moderately differentiated adenocarcinomas and rare in poorly differentiated tumors, which slightly differs from previous research suggesting a lower mutation rate in poorly differentiated cases." (PMID 41378298, 2025). "Additionally, studies mapping the phylogenetic evolution of GBM have revealed that mutations in EGFR tend to accumulate at later stages of tumor development, while alterations in PI3KCA occur earlier." (PMID 40149830, 2025). "For example, activating mutations in the RAS genes (KRAS/NRAS) renders a tumor unresponsive to therapy with monoclonal antibodies against the epidermal growth factor receptor (EGFR) (cetuximab, panitumumab), which is effective only in the absence of such mutations (RAS wild-type)." (PMID 41155400, 2025). "Interestingly, only the loss of SMARCA2 was found concomitant with the presence of tumor lepidic components and epidermal growth factor receptor (EGFR) mutations, whereas the loss of SMARCA4 was mutually exclusive with those findings." (PMID 39888726, 2025). "Betacellulin (BTC) proteins are ligands for the EGFR/ERBB4 ligand, with established literature showing that BTC overexpression by HCC cells and EGFR expression by tumor-associated endothelial cells collaboratively enhance tumor vascularity via paracrine signaling." (PMID 40906438, 2025). "Then, the novel method was applied to detect the EGFR gene mutations in tumor samples." (PMID 40587690, 2025). "However, the on-target and off-target aberrations can co-occur within the same tumor and co-exist with EGFR tertiary mutations that arise from the complexity and heterogeneity of cancer evolution driven by EGFR TKI treatment." (PMID 40002158, 2025).
tumor (continued). "The study also showed that IL-1β blockade could prevent particulate matter-induced tumor formation in mouse models with EGFR and KRAS mutations." (PMID 40940992, 2025). "When EGFR is mutated, cell growth becomes uncontrolled, and the cells become a tumor." (PMID 39907159, 2025). "In response to EGFR-TKI therapy, certain tumor cells may exhibit upregulation of genes associated with alternative signaling pathways that bypass EGFR blockade." (PMID 40486879, 2025). "Additionally, for assessing the infiltration levels of multiple immune cells to estimate the tumor microenvironment, CIBERSORTx was performed using transcriptome data obtained from EGFR-mutated NSCLC tumor developing resistance to EGFR-TKIs." (PMID 41001033, 2025). "Notably, a statistically significant association was observed between tumor laterality and EGFR status (p = 0.045), EGFR mutations more commonly detected in right-sided tumors (23.9%) compared to left-sided tumors (6.5%)." (PMID 41327362, 2025). "Spiculation sign and pleural indentation, markers of desmoplastic reactions, have been linked to tumor invasiveness and reduced differentiation in EGFR-mutant adenocarcinomas, which may explain their association with Napsin A negativity in our cohort." (PMID 40687424, 2025). "Furthermore, EGFR mutations were linked to a lower tumor mutational burden (TMB) in comparison to wild-type EGFR, offering a scientific justification and a possible explanation for this subgroup’s poor immunotherapy response." (PMID 40361442, 2025). "EGFR is a member of the ErbB family of receptor tyrosine kinases that regulate cell proliferation, survival, adhesion, migration, and differentiation; in certain tumor types, its expression has been associated with poor clinical outcomes." (PMID 41155410, 2025). "In addition, KRAS-mutated patients carry, on average, a higher tumor mutation burden than EGFR-mutated patients." (PMID 40299444, 2025). "Similarly, clinically important EGFR variants were present in tumor tissues from 14 (54%) stage I, 9 (24%) stage II, 5 (11%) stage III, and 5 (55%) stage IV cases in the cohort." (PMID 40282516, 2025). "EGFR gene mutations are particularly important in guiding clinical therapeutic regimens, but their detection is often limited by factors such as difficulty in sourcing tumour tissues, technical complexity, and high cost." (PMID 40438325, 2025). "Real-time monitoring of ctDNA is a promising tool for tailoring adjuvant treatment, given the established role of molecular residual disease in predicting DFS after radical surgery for EGFR-mutated tumours, but it is still far from being implemented in clinical practice." (PMID 40628491, 2025). "CD49b was expressed in 71.11% (32/45) of normal tissues, CD73 in 86.05% (37/43), and EGFR in 46.67% (21/45), which may cause more on-target-off-tumor toxicities in contrast to ICAM1 in 19.15% (9/47)." (PMID 39971940, 2025). "Furthermore, homologous frameshift DNA methylation has been implicated as a novel tumor cell state involved in intrinsic resistance to EGFR-TKI therapy." (PMID 40003951, 2025). "Moreover, some researches discovered that the identical EGFR mutation patterns in the squamous cell carcinomatous and the adenocarcinomatous components in each patient, indicated the monoclonality of the two tumor components in ASC patients." (PMID 39026979, 2024). "Additionally, the tracer successfully visualized tumors regardless of KRAS mutation status, a factor known to induce anti-EGFR resistance and that can decrease tumor uptake." (PMID 39768978, 2024).
tumor (continued). "The most common activating EGFR mutation based on tumor genotyping was exon 19 deletion (64%), followed by exon 21 L858R (34%) and all patients had EGFR T790M confirmed through tumor (45%) and/or ctDNA analysis (55%), based on local laboratory testing at each participating site." (PMID 38418463, 2024). "Cetuximab, an EGFR inhibitor, was significantly associated with higher tumor response." (PMID 38336718, 2024). "Also, in Spearman’s correlation analysis, the neoplastic cellularity of tumor specimens was positively correlated with the EGFR variant read frequency (Spearman’s rank correlation coefficient = 0.40, p = 0.0046)." (PMID 39063150, 2024). "Importantly, the functions induced by anti-TGF-β or anti-PD-1 monotherapy were further enhanced by the combination of anti-TGF-β and anti-PD-1 treatments, contributing to the significant reduction in EGFR-mutated tumor growth in vivo." (PMID 39004699, 2024). "Therefore, further studies are necessary to explore the detailed mechanisms underlying EGFR-mediated cancer cell proliferation and tumor growth." (PMID 38745775, 2024). "Afatinib shows some activity not only against classical EGFR but also HER2-mutated tumours." (PMID 38891886, 2024). "High SUVmax values are frequently observed in EGFR-mutated cases, supporting the hypothesis that PD-L1 expression promotes an inflammatory tumor microenvironment, enhancing glucose metabolism and FDG uptake." (PMID 39902124, 2024). "EGFR mutations in the peripheral blood ctDNA and tumor tissues." (PMID 39634906, 2024). "These tumor images were input into a convolutional neural network model to extract 512 image features, which were combined with radiographic features and clinical data to predict the EGFR mutation." (PMID 38195717, 2024). "Moreover, CAL, E-Cad, and epidermal growth factor receptor (EGFR) represent essential tumor markers, originally used in human tumor diagnostic." (PMID 39409848, 2024). "EGFR mutation in peripheral blood and tumor tissues is highly consistent in NSCLC patients." (PMID 39634906, 2024). "A singleplex test with a short TAT may be beneficial in identifying EGFR or ALK mutations in patients with elevated specific tumor markers." (PMID 38400801, 2024). "We analyzed local control in patients with adenocarcinoma and unknown EGFR mutation status revealed slightly larger tumor shrinkage in patients treated with erlotinib, but the differences are not significant and the numbers are small." (PMID 39148905, 2024). "Importantly, EGFR mutations predominantly occur in exons 19 and 21 (L858R, L861Q), significantly impacting tumor sensitivity to EGFR-TKI therapy." (PMID 38980474, 2024). "The EGFR signaling pathway is also associated with immune suppression in the tumor microenvironment, and blocking this pathway may reduce tumor immune evasion." (PMID 39741907, 2024). "The signal transduction of EGFR tyrosine kinase is strongly linked to tumor progression." (PMID 39569013, 2024). "EGFR overexpression is associated with tumor metastasis, invasion and poor prognosis." (PMID 38903179, 2024). "Hence, targeting CBL-c is a promising strategy for inhibiting tumor growth and improving the response to tyrosine kinase inhibitor treatment in EGFR-mutated NSCLC." (PMID 39130630, 2024). "Previously, we showed our custom-designed cationic lipid MB could deliver EGFR siRNA to SCC-VII tumor cells using a diagnostic US pulse available on a clinical system, trigger target gene silencing, and induce tumor growth inhibition." (PMID 38577322, 2024). "However, in the TKI treated group, the frequency of EGFR sensitizing mutation and T790M resistance mutation in specimens with < 20% tumor cellularity was significantly lower than that in specimens with ≥ 20% tumor cellularity." (PMID 38902688, 2024). "Therefore, the model that combined clinical data, radiomics features extracted from the CT images, and tumor images achieved the best EGFR mutation prediction performance." (PMID 38195717, 2024).